YY1 (YY1 transcription factor)
Diseases named in the same sentence as YY1 in open-access papers (continued):
Sharing a sentence is not in itself a finding about the gene and the disease.
pancreatic cancer (continued). "YY1 could suppress the invasion and proliferation of pancreatic cancer cells through MUC4/ErbB2/p38/mef2cMEF2C-dependent mechanism." (PMID 35359580, 2022). "Moreover, authors found that YY1 transcriptionally activated miR-135b and formed a “miR-135b-BMAL1-YY1” loop, which has significant predictive and prognostic value for patients with pancreatic cancer." (PMID 33042011, 2020). "YY1 was also reported to be a downstream target of NF‐κB in myoblasts and pancreatic cancer cells." (PMID 33040438, 2020). "In vivo experiments revealed that YY1 could inhibit the migration and invasion of pancreatic cancer cells by downregulating the expression of TPPP/p25 via p38/MAPK and PI3K/AKT pathways with undefined mechanism." (PMID 32033023, 2020). "Importantly, Kras and NFκB concomitantly induce expression of Yin Yang 1 (YY1) transcription factor in pancreatic cancer." (PMID 32929330, 2020). "Finally, we found that the upregulation of TPPP also restored the inhibitory effect of YY1 overexpression on pancreatic cancer angiogenesis." (PMID 31631174, 2019). "In addition to regulating the lncRNA SOX2OT, YY1 was also shown to repress miR-30a, in pancreatic cancer cells and thereby suppress pancreatic tumor growth presumably by modulating autophagy." (PMID 31824839, 2019). "In this context, it remains to be tested whether the YY1 interactome is significantly different in pancreatic cancer compared to other cancers." (PMID 31824839, 2019). "Further experiments showed that YY1 could inhibit the migration, invasion and angiogenesis of pancreatic cancer cells by downregulating TPPP via p38/MAPK and PI3K/AKT pathways." (PMID 31631174, 2019). "However, surprisingly, YY1 has also been reported to play a tumor suppressor role particularly in the case of pancreatic cancer." (PMID 31824839, 2019). "In addition, TPPP promoted the migration, invasion and angiogenesis of pancreatic cancer cells, and was regulated by the transcription factor YY1." (PMID 31631174, 2019). "YY1 was confirmed to regulate autophagy in pancreatic cancer cells." (PMID 29052509, 2017). "Taken together, YY1 likely plays roles in autophagy in pancreatic cancer cells." (PMID 29052509, 2017). "This study investigated potential roles for YY1 in autophagy in pancreatic cancer cells." (PMID 29052509, 2017). "Since ATG5 and Beclin 1 are both known to be direct targets of miR-30a, we hypothesized that YY1 and miR-30a might form a functional regulatory circuit that modulates autophagy in pancreatic cancer cells." (PMID 29052509, 2017). "Furthermore, miR-30a regulates the expression of YY1, suggesting a novel YY1/miR-30a regulatory circuit that controls autophagy in pancreatic cancer cells." (PMID 29052509, 2017). "In addition, YY1 expression correlated with BAX expression in pancreatic cancer tissues, also suggesting that YY1 positively regulates the expression of BAX." (PMID 27074573, 2016). "We presumed that YY1 is not a causal factor of pancreatic cancer; however, during the development of pancreatic cancer, the human body provides feedback on increased expression of tumor suppressor gene YY1." (PMID 24884523, 2014). "Thus, autophagy in pancreatic cancer cells may be regulated, in part, by a tightly coordinated YY1/miR-30a regulatory circuit." (PMID 29052509, 2017). "Therefore, pancreatic cancer patients with high-level overexpression of YY1 show good prognosis." (PMID 24884523, 2014). "Two examples, erdafitinib (FGFR inhibitor) and sotorasib (KRAS G12C inhibitor) impaired YY1 expression in genotype-matched bladder cancer cell line RT112 and pancreatic cancer cell line MIA PaCa-2, respectively." (PMID 39604408, 2024). "ChIP sequencing results showed that YY1 directly binds to the promoter region of TPPP and thus inhibits pancreatic cancer cell migration, invasion and angiogenesis." (PMID 37081988, 2023).
pancreatic cancer (continued). "Collectively, YY1 inhibits FER expression, which in turn results in impaired STAT3-MMP2 pathway leading to suppression of pancreatic cancer growth." (PMID 31824839, 2019). "In contrast to its transcriptional repressive function, YY1 as a transcriptional activator was shown to induce the expression of the pro-apoptotic BAX gene and induce apoptosis of pancreatic cancer cells and prevent tumor growth." (PMID 31824839, 2019). "First, YY1 binds to the promoter of MUC4 and negatively regulates the expression of this well-known pancreatic cancer-related gene." (PMID 24884523, 2014). "However, YY1 could play a tumor suppressor role in inhibiting pancreatic cancer progression." (PMID 24884523, 2014). "Collectively, while YY1 largely plays a tumor suppressive role in pancreatic cancer, it is not clear as to how YY1 levels were maintained relatively low in pancreatic cancer compared to other cancer tissues." (PMID 31824839, 2019). "A report indicated that YY1 could suppress invasion and metastasis by downregulating MMP10 in a MUC4/ErbB2/p38/MEF2C-dependent manner in pancreatic cancer cells, suggesting MEF2C phosphorylation is required for MMP10 expression." (PMID 30836712, 2019). "Combined with our previous work, YY1 appears to play critical roles in pancreatic cancer—not only in tumor cell growth, progression, and invasion, but also in autophagy." (PMID 29052509, 2017). "In particular, the relationship between YY1 and autophagy in pancreatic cancer cells has not been reported." (PMID 29052509, 2017). "For instance, our previous study revealed that the expression of YY1 in pancreatic cancers is elevated compared to adjacent non-tumor tissues and normal pancreatic tissues." (PMID 29052509, 2017). "We measured YY1 and BAX mRNA levels in 50 pancreatic cancer samples using quantitative RT-PCR." (PMID 27074573, 2016). "In addition, among the 205 upregulated genes, the pancreatic cancer-related gene MUC4 was upregulated by 4.0-fold, indicating that YY1 may negatively regulate MUC4 gene expression." (PMID 24884523, 2014).
colon carcinoma (36 papers, 2010 to 2025). "For example, GLUT3 is transactivated by Ying Yang 1 (YY1) and promotes the Warburg effect of colon carcinoma." (PMID 40787462, 2025). "Physiologically, YY1 is over-expressed in several malignancies, including metastatic breast cancer, colon cancer, gastric cancer, and prostate cancer." (PMID 38351178, 2024). "Herein, we first report that MOF was bound to and acetylated YY1, and this modification regulated ubiquitin-proteasome degradation of YY1 in human colon carcinoma cells." (PMID 37240065, 2023). "For example, the clinical drug oxaliplatin was reported to suppress colon carcinoma cell proliferation and angiogenesis by inhibiting the YY1/GLUT3 axis." (PMID 37081988, 2023). "The expression of YY1 is significantly increased in colon cancer and subjected to O-GlcNAcylation modifications, which increases the stability and transcriptional activity of YY1, thus promoting tumor proliferation." (PMID 35359580, 2022). "Other studies showed that Linc01578 facilitated the metastasis of colon cancer by forming a positive feedback loop with NF-κB/YY1 and suggested Linc01578 as a potential biomarker for prognosis and therapeutic target for colon cancer metastasis." (PMID 35370745, 2022). "YY1 has also been shown to suppress the Fas promoter activity in B-non-Hodgkin's lymphoma and colon cancer." (PMID 34597666, 2021). "In colon cancer cell lines, the ectopic expression of YY1 stimulated cell growth and suppressed apoptosis, and it was targeted and inhibited by miR-7." (PMID 32153636, 2020). "Linc01578 enhances tumor metastasis via modulation of NF-κB and Yin Yang 1 (YY1) axis in colon cancer." (PMID 33246471, 2020). "In colon cancer, particularly, Yy1 has a pro-tumorigenic role and it is responsible for high grade metastasis, drug resistance and promotion of stem cell-specific transcriptional programs, including the Wnt/β catenin pathway." (PMID 32927726, 2020). "LINC01578 enhanced colon cancer liver metastasis through forming a positive feedback loop with NF‐κB/YY1." (PMID 33040438, 2020). "The correlation between LINC01578 and NF‐κB/YY1 was also verified in clinical colon cancer tissues and colon cancer liver metastasis." (PMID 33040438, 2020). "LINC01578 enhances colon cancer cell viability, mobility, and in vivo metastasis through forming a positive feedback loop with NF‐κB/YY1." (PMID 33040438, 2020). "In colon cancer, YY1 promotes the growth and Wnt signaling pathway of cancer cells through inhibiting p5358." (PMID 32042322, 2020). "Overexpression of YY1 has been observed in prostate, ovarian, and colon cancer.YY1 has been proposed as a potential prognostic factor for cancer patients, based on its role in cancer development." (PMID 27074573, 2016). "We also report about the finding of a significant regulatory activity of the YY1 protein over a set of oncomiRNAs related to the colon cancer." (PMID 20398296, 2010). "Our findings offer a theoretical foundation for clarifying how YY1 functions in colon cancer cells." (PMID 37240065, 2023). "In addition, YY1 regulates the upregulation of metabolite transporter expression, which in turn promotes the survival and proliferation of colon cancer cells." (PMID 35359580, 2022). "The expression of YY1 was positively correlated with that of LINC01578 in colon cancer tissues." (PMID 33040438, 2020). "Given that NF‐κB and YY1 directly upregulated LINC01578, LINC01578 and NF‐κB/YY1 may form positive feedback loop in colon cancer." (PMID 33040438, 2020). "YY1 is a structural regulator of enhancer-promoter interactions and facilitates gene expression.The overexpression of YY1 occurs in a range of cancer types, including lung, gastric, and colon cancer." (PMID 32153636, 2020). "Furthermore, the effects of NF‐κB and YY1 on LINC01578 were also verified in another colon cancer cell line HT‐29." (PMID 33040438, 2020).
colon carcinoma (continued). "Collectively, this study demonstrated that LINC01578 promoted colon cancer metastasis via forming a positive feedback loop with NF‐κB/YY1 and suggested that LINC01578 represents a potential prognostic biomarker and therapeutic target for colon cancer metastasis." (PMID 33040438, 2020). "Collectively, in colon cancer, YY1 is largely a tumor promoter and an attractive drug target." (PMID 31824839, 2019). "Thus, targeting YY1 O-GlcNAcylation could serve as an attractive therapeutic strategy for colon cancer treatment." (PMID 31824839, 2019). "In some cases, high expression of YY1 correlated with poor prognosis (such as in prostate, breast and bone cancers), whereas in other situations, YY1 expression correlated with favorable outcomes (such as in ovarian cancer, colon cancer and follicular lymphoma)." (PMID 24884523, 2014). "LPS induces histone Kla at the LINC00152 promoter and decreases its binding efficiency to the transcription factor yin-yang 1 (YY1), leading to increased LINC00152 expression, thereby promoting the migration and invasion of colon cancer cells." (PMID 37646027, 2023). "As expected, overexpression of YY1 remarkably increased the clonogenic ability of both HCT116 and SW480 colon cancer cells; however, the YY1K183R mutant lost its ability to promote colony formation." (PMID 37240065, 2023). "Overexpressed YY1 and MOF in HCT116 colon cancer cells immunoprecipitated endogenous MOF and YY1, respectively." (PMID 37240065, 2023). "A previous study exhibited that transcription factors YY1 and ELK1 bound to the miR-320-3p promoter and increased miR-320-3p expression in cervical cancer and colon cancer cells." (PMID 35054986, 2022). "Thus, we next studied whether NF‐κB and YY1 modulated LINC01578 expression in colon cancer." (PMID 33040438, 2020). "Consistent with LINC01578, YY1 was also increased in colon cancer tissues with metastasis with respect to colon cancer tissues without metastasis." (PMID 33040438, 2020). "To investigate whether this positive feedback loop also exists in colon cancer metastasis in vivo, we measured the expression and correlation between LINC01578, NFKBIB, and YY1 in clinical tissues." (PMID 33040438, 2020). "YY1 (Yin‐Yang‐1) is a zinc‐finger transcription factor that belongs to the GLI‐Krüppel gene family 8 and abnormally expressed in lots of cancer such as colon cancer 9, non‐small‐cell lung cancer 10, and myeloma 11, indicating that it has key roles in carcinogenesis." (PMID 28485541, 2017).
glioma (29 papers, 2014 to 2026). A benign or malignant brain and spinal cord tumor that arises from glial cells (astrocytes, oligodendrocytes, ependymal cells). "Indeed, the TUG1 lncRNA does just that, as it acts as a scaffold for PRC2 and YY1 to repress YY1-target genes associated with neuronal differentiation in glioma." (PMID 37444543, 2023). "YY1 or Yin Yang 1 transcription factor is known to regulate a number of proteins associated with cell division, differentiation, and DNA repair; and a number of evidences indicate its role in the progression of glioma." (PMID 34900729, 2021). "The results from the EdU and Transwell assays further confirmed that YY1 can promote the proliferation, invasion, and migration abilities of glioma cells by regulating USP18." (PMID 40374599, 2025). "In gliomas, IDH1 mutations disrupt chromosomal neighborhoods through CTCF hypermethylation, while YY1 mediates chromatin loops and transcription elongation." (PMID 40565099, 2025). "Recent studies have shown a YY1 upregulation during the progression of the disease, increasing from benign meningiomas to low-grade gliomas and reaching major levels in glioblastoma multiforme." (PMID 39904836, 2025). "Bioinformatics analysis also revealed a positive correlation between the expression levels of USP18 and YY1 across multiple glioma public databases." (PMID 40374599, 2025). "On the other hand, miR-218 can target YY1 directly in glioma cells, inhibiting its function and suppressing cell proliferation promoted by YY1." (PMID 39904836, 2025). "The lncRNA KB-1460A1.5 regulates TSC1 expression by sponging miR-130a-3p and participates in miR-130a-3p/TSC1/mTOR/YY1 feedback loop to inhibit glioma tumorigenesis." (PMID 38725030, 2024). "Mechanistically, circPTPRF acts as a sponge for miR-1208, relieving its inhibition of YY1 expression and promoting the progressive phenotypes of glioma." (PMID 38893192, 2024). "The expression of circ_0001588 was markedly up-regulated in glioblastoma tissues and human gliomas cells, moreover, circ_0001588 accelerated the proliferation, migration and invasion of glioblastoma by modulating miR-211-5p/YY1 signaling." (PMID 36439541, 2022). "Then, we used the GEPIA database to analyze the correlation between these transcription factors and YTHDF2 expression in glioma samples based on the TCGA and CGGA dataset and found that only YY1 was positively associated with YTHDF2 expression." (PMID 35661004, 2022). "Our study is the first research that verifies circPTPRF/miR-1208/YY1 axis participates in glioma progression." (PMID 36397164, 2022). "The findings that YY1-induced SNHG17 facilitated the glioma progression through targeting miR-506-3p/CTNNB1 axis to activate Wnt/β-catenin signaling pathway offered a brand-new prospects to molecular-targeted treatment for glioma." (PMID 32009853, 2020). "We analyzed relationship between SNHG17 and YY1 expression among 33 glioma tissues and found that YY1 was positively correlated with SNHG17." (PMID 32009853, 2020). "SNHG17 induced by YY1 facilitated the glioma progression through targeting miR-506-3p/CTNNB1 axis to activate Wnt/β-catenin signaling pathway." (PMID 32009853, 2020). "All the data implied that YY1 increased the expression of SNHG17 through binding with SNHG17 promoter to boost the development of glioma." (PMID 32009853, 2020).